CDH1 (cadherin 1)
Diseases named in the same sentence as CDH1 in open-access papers (continued):
Sharing a sentence is not in itself a finding about the gene and the disease.
gastric cancer (continued). "Even so, the indolent nature of SRC lesions arising due to germline CDH1 P/LP variants strongly suggests that these individuals should not be treated the same as those with sporadic (nonsyndromic) gastric cancers." (PMID 39760880, 2025). "The identification of CDH1 mutations in families with a history of gastric cancer has led to the establishment of specific testing criteria, enabling targeted genetic counseling and management strategies." (PMID 40585607, 2025). "Prophylactic total gastrectomy (PTG) is often recommended for individuals with confirmed CDH1 mutations, particularly given the tendency for gastric cancer to present at an advanced stage with minimal prior symptoms." (PMID 40585607, 2025). "Variants in CDH1, a gene associated with hereditary gastric cancer, were found in only 5.1% of the cases." (PMID 40514520, 2025). "Individuals with CDH1 mutations face a cumulative risk of gastric cancer that can reach up to 83% by age 80, with women having a slightly higher risk compared to men." (PMID 40585607, 2025). "CRC often recurs, particularly in patients with CHEK2 mutations, while gastric cancer was found to be frequent in individuals with CDH1 mutations." (PMID 40649708, 2025). "Assessment of gastric cancer risk due to CDH1 P/LP variants is complex, and the onus is on clinicians to correctly interpret individual cancer risk, because risks of both missed diagnoses and overtreatment can be severe." (PMID 39760880, 2025). "Prophylactic gastrectomy in CDH1-mutation carriers: Psychosocial, physical, and nutritional effect compared with curative gastrectomy for gastric cancer." (PMID 40551901, 2025). "Regression analysis suggested that elevated CDH1 mRNA increased gastric cancer risk, while E-cadherin cytoplasmic ectopic expression heightened the risk of precancerous lesions and gastric cancer." (PMID 40416864, 2025). "One of the key molecular characteristics of CDH1-related gastric cancer is the high tumor mutation burden (TMB) observed in some cases." (PMID 40585607, 2025). "RRTG is associated with life-changing adverse events that should be discussed when counseling patients with CDH1 variants about gastric cancer prevention." (PMID 37903316, 2024). "The study investigates the role of the CDH1 gene's C-160A SNP in susceptibility to gastric cancer through a systematic review and meta-analysis." (PMID 39355481, 2024). "Genetic mutations such as the CDH1 germline mutation or hMLH1 germline mutations make up 2–3% of early-onset gastric cancer cases in North America." (PMID 38672634, 2024). "Impaired E-cadherin (Cdh1) functions are closely associated with cellular dedifferentiation, infiltrative tumor growth and metastasis, particularly in gastric cancer." (PMID 39000189, 2024). "We elucidated the burden of total gastrectomy for prevention of advanced gastric cancer in individuals with CDH1 P/LP variants." (PMID 37903316, 2024). "Hereditary diffuse gastric cancer (HDGC) is an autosomal dominant cancer syndrome attributed to germline mutations within CDH1 which is responsible for up to 3% of all gastric cancers." (PMID 36869400, 2023). "Until recently, prophylactic gastrectomy was recommended for all CDH1 carriers, as the risk of gastric cancer was estimated to be over 70% for all families." (PMID 37761816, 2023).
gastric cancer (continued). "Significant associations were found in Māori kindred carrying CDH1 germline pathogenic variants for gastric cancer risk, as well as in Ashkenazy Jewish and Hakka Chinese populations with BRCA variants for BC risk." (PMID 36612302, 2023). "A significant portion of 16 new variants were found in the TTN gene, including the two high-impact variants, and the other new variant, the INDEL type, was found in the CDH1 gene, which is highly associated with the development of Gastric Cancer." (PMID 37763132, 2023). "The cumulative risk of developing gastric cancer for CDH1 pathogenic variant carriers in their lifetime is estimated to be 70%, and there is also a 42% risk of lobular breast cancer (LBC) for women." (PMID 37393258, 2023). "The cumulative risk of DGC in CDH1 carriers has been recently reassessed (from 40–83% by age 80 to 25–42%) and varies according to the presence and number of gastric cancers in the family." (PMID 37761816, 2023). "In our study, the CDH1 deletion variant(seq[hg19]chr16:68760000-69040000(del)) was identified in a fetus with gastric cancer and breast cancer history." (PMID 37393258, 2023). "Diffuse gastric cancer is often associated with genetic mutations and molecular changes, including mutations in the CDH1 gene, which is associated with hereditary diffuse GC." (PMID 37894471, 2023). "For CDH1 pathogenic variant carriers, early detection and treatment measures of gastric cancer can be taken, and the most effective preventive measure is total gastrectomy." (PMID 37393258, 2023). "There were significantly fewer patients with gastric cancer/CDH1 gene mutation and more with esophageal cancer in IG (p = 0.001)." (PMID 36831145, 2023). "Patients with gastrointestinal cancer were divided into subgroups (esophageal cancer, gastroesophageal junction cancer, gastric cancer, CDH1 gene mutation), and analysis was performed by comparing two groups (IG versus CG)." (PMID 36831145, 2023). "While prophylactic gastrectomy is recommended for pathogenic CDH1 variant carriers from families with gastric cancer between 20 and 30 years of age, the recommendation for families without DGC is not straightforward." (PMID 37761816, 2023). "HDGC is the most common cancer predisposition for gastric carcinoma and is caused by germline variants in CDH1 and CTNNA1." (PMID 36612313, 2023). "A meta-analysis that included more than 2500 gastric cancer patients suggested that, for example, E-Cadherin (CDH1) polymorphism renders the Asian population more susceptible towards the development of gastric cancer." (PMID 35326507, 2022). "At the time of initiation of this study, it was estimated that 70% of patients who inherited the CDH1 gene mutation would develop gastric cancer." (PMID 35158993, 2022). "Mutations in the CDH1 gene are the most frequently detected germline mutations in gastric cancer and are responsible for the development of hereditary diffuse gastric cancer (HDGC) syndrome." (PMID 35509706, 2022). "At present, most studies about hereditary gastric cancer focused on germline mutations of tumor suppressor genes CDH1 (E-cadherin)." (PMID 35689286, 2022). "Given that little is known about the reproductive attitudes of individuals with HDGC, we recruited participants with CDH1 variants from a familial gastric cancer registry and administered a cross-sectional survey with open- and closed-ended response items." (PMID 36056367, 2022). "Although familial clustering of gastric cancer was initially described in a multigenerational Maori family from New Zealand in 1964, Guilford and colleagues first identified CDH1 germline variants as being a cause of the familial cancer in 1998." (PMID 36056367, 2022). "Alternatively, germline mutations of CDH1 germline were additionally found in some patients with early onset gastric cancer who are usually younger than 35 years upon diagnosis." (PMID 35418175, 2022).
gastric cancer (continued). "For example, in New Zealand, CDH1 mutation carriers have developed gastric cancer in their mid-teens; as a consequence, genetic testing begins at 16 years of age, and occasionally 1–2 years before, on a case-by-case basis." (PMID 36556253, 2022). "This study reports the long-term results of total gastrectomy for patients with a family history of gastric cancer and CDH1 gene mutations that predispose to hereditary diffuse gastric cancer (HDGC)." (PMID 35158993, 2022). "Despite the high incidence of gastric cancer in East Asian countries, previous work has suggested that low detection rates for germline CDH1 variants are identified in Asians compared to countries with a lower incidence of gastric cancer." (PMID 34949788, 2022). "The lifetime risk of developing gastric cancer in individuals carrying a mutation in CDH1 gene is estimated to be less than 1% at the age of 20, around 4% by the age of 30, increasing to about 20% for men and 45% for women by the age of 50." (PMID 36556253, 2022). "While CDH1 mutations are found mostly in stomach cancer, they are also shown to be frequently occurring in lobular breast cancer." (PMID 34997044, 2022). "Prophylactic gastrectomy in early adulthood is recommended by the International Gastric Cancer Linkage Consortium (IGCLC) as a standard of care in patients with pathogenic CDH1 mutation associated with a family history of diffuse-type GC." (PMID 36428634, 2022). "Using the criteria for HDGC, the detection rate of CDH1 pathogenic or likely pathogenic variants is detected in 48% of families with multiple cases of gastric cancer." (PMID 36556253, 2022). "The CDH1 gene, encoding the cell adhesion protein E-cadherin, is one of the most frequently mutated genes in gastric cancer and inactivating germline CDH1 mutations are responsible for the cancer syndrome hereditary diffuse gastric cancer (HDGC)." (PMID 35406381, 2022). "They all confirmed that a higher rate of somatic CDH1 mutations was observed in early-onset gastric cancer patients, while our large cohort study further consolidates this phenomenon." (PMID 35498538, 2022). "CDH1 mutation carriers harbor an approximately 70% lifetime risk to develop gastric cancer for male gender and 56% in women." (PMID 35887173, 2022). "Beyond that, genetic factors have a profound impact on gastric cancer; it seems that E-cadherin (cdh1) mutation leads to a specific type of gastric cancer called hereditary diffuse gastric cancer." (PMID 35650297, 2022). "The median age of onset of breast, colorectal, and gastric cancers among patients with CDH1 P/LP variants was lower than that of the general population from the SEER cohort." (PMID 34949788, 2022). "CDH1 mutations are the most common germline mutations detected in gastric cancer and underlie HDGC syndrome." (PMID 35887173, 2022). "The NMD mRNA surveillance pathway downregulates aberrant E-cadherin transcripts in gastric cancer cells and in CDH1 mutation carriers." (PMID 36620557, 2022). "Genetic studies identified a dozen of frequently mutated genes in gastric cancer, such as cadherin 1 (CDH1) and A-kinase anchoring protein 9 (AKAP9)." (PMID 36317124, 2022). "Prophylactic gastrectomy is indicated for any patient with a family history of gastric cancer and a CDH1 mutation." (PMID 35158993, 2022). "Precursor lesions of invasive gastric cancer have been identified in CDH1 mutation carriers as in situ signet ring cell carcinoma (SRCC) or pagetoid spread of signet ring cells below the preserved epithelium of glands." (PMID 34486077, 2022). "CDH1-deficient gastric cancers exhibit high AKT serine/threonine kinase 3 (AKT3) expression, but specific drugs against this AKT isoform are not available." (PMID 35406381, 2022). "Genetic susceptibility to colorectal and gastric carcinoma has been correlated with CDH1 (E-cadherin) mutations." (PMID 36161592, 2022).
gastric cancer (continued). "As results, we detected one large rearrangement causing a premature stop in exon 3 of the CDH1 gene in a proband with a bilateral lobular breast carcinoma and a gastric carcinoma (GC)." (PMID 36553480, 2022). "In this systematic review, we collected and analyzed all studies describing CDH1 variants in gastric cancer patients originating from both high- and low-prevalence countries." (PMID 33809393, 2021). "Some patients carry a mutated copy of the CDH1 gene that can lead to a very rare form of hereditary gastric cancer called signet-ring cell adenocarcinoma (SRCC)." (PMID 34073553, 2021). "It is not clear either why CDH1 mutations are linked primarily with gastric cancer and an increased risk of lobular breast cancer, although case reports document the co-existence of CDH1 gastric SRCC with colorectal, appendiceal, and pancreatic cancers." (PMID 34073553, 2021). "Brain tumors were observed in three of 28 (10.7%) gastric cancer families with pathogenic CDH1 variants." (PMID 33929593, 2021). "It has been documented that mutations affecting the CDH1 gene result in several types of cancers including ovarian, thyroid, colorectal, breast, and gastric cancers." (PMID 33869191, 2021). "Research confirms that CDH1 mutations are more likely to be found in countries with a low incidence of gastric cancer.Thus preventive genetic screening is very important." (PMID 34422902, 2021). "Among these, germline defects in CDH1, encoding the epithelial cadherin, have been particularly explored in the context of both familial and sporadic gastric cancer development." (PMID 33809393, 2021). "As brain tumors occurred in three of 68 individuals from gastric cancer families with pathogenic CDH1 variants, the prevalence was significantly higher in our gastric cancer cohort (4.4%) than in the general population (0.2%)." (PMID 33929593, 2021). "In 68 individuals from 28 gastric cancer families with pathogenic CDH1 germline variants, brain tumors, including a pituitary adenoma, were observed in three cases (4.4%), a significantly higher prevalence than in the general population (0.2%)." (PMID 33929593, 2021). "Prophylactic total gastrectomy is indicated in confirmed familial hereditary gastric cancer with the CDh1 gene mutation." (PMID 34008707, 2021). "We observe that, along with other host genetic and environmental factors, CDH1 missense variants are associated to the high incidence of gastric cancer in Asian populations." (PMID 33809393, 2021). "Genetically, the main oncogene of gastric cancer is CDH1 (E-cadherin) as many pathogenic variants are associated with familial diffuse-type gastric cancer." (PMID 33482814, 2021). "In gastric cancer, diffuse gastric cancer is more closely related to E-cadherin expression and CDH1 mutations." (PMID 34422902, 2021). "Our results indicate that CDH1 mutations are more frequently identified in gastric cancer low-incidence countries, and in the family study group that encompasses cases fulfilling criteria." (PMID 33809393, 2021). "Patients with gastric cancer and germline CDH1 mutations have a lower survival rate than patients who meet the HDGC criteria but do not have the CDH1 mutations." (PMID 33941229, 2021). "In line with our findings, brain tumors have previously been reported in gastric cancer families with causative germline alterations in CDH1 and other (suspected) tumor suppressor genes, e.g. ATM, CTNNA1, and SDHB." (PMID 33929593, 2021).
gastric cancer (continued). "Third, inherited mutations of certain genes such as glutathione S-transferase mu 1-null phenotype and cadherin 1 are known risk factors for gastric cancer and contribute to 1–3% of all gastric cancers." (PMID 34442208, 2021). "We have therefore used cases of sporadic gastric SRCCs in SEER to crudely estimate possible secondary cancer risks in our CDH1 mutation patients, recognizing that SRCCs comprise 10–18% of all gastric cancer cases whereas HDGC are fewer at 1–3%." (PMID 34073553, 2021). "Loss of E-cadherin expression is closely related to the sporadic and genetic forms of gastric cancer, and CDH1 mutation is one of the important reasons for the loss of E-cadherin expression." (PMID 34422902, 2021). "Next, we determined the prevalence of brain tumors in gastric cancer families carrying pathogenic CDH1 germline variants." (PMID 33929593, 2021). "In this study we aimed to assess the worldwide frequency of CDH1 germline mutations in gastric cancers coming from different geographical areas, using a systematic approach." (PMID 33809393, 2021). "In a cohort of 28 gastric cancer families with pathogenic CDH1 germline variants, brain tumors were observed in three of 68 (4.4%) individuals, a significantly higher prevalence than in the general population (0.2%)." (PMID 33929593, 2021). "In human samples, somatic CDH1 alterations are associated with poor survival and worse prognosis in gastric cancer patients." (PMID 34066044, 2021). "Mutations in CDH1 were more frequent in younger stomach cancer patients (OR = 0.9414, 95% CI = 0.9027–0.9800, adj." (PMID 33879792, 2021). "LOXL1 overexpression reduced CDH1 expression and promoted the migration capacity of gastric carcinoma cells and associates LOXL1 with peritoneal dissemination in gastric cancer possibly via promotion of EMT." (PMID 33616307, 2021). "The mutation or deletion of CDH1 (E-cadherin gene) can be found in some hereditary gastric cancers but it is also common in familiar cases." (PMID 32348353, 2020). "Frequencies of CDH1 germline mutations in gastric cancer have been known to vary according to the incidence of gastric cancer 3,20." (PMID 31892987, 2020). "In 1999 the International Gastric Cancer Linkage Consortium (IGCLC) first published guidelines to select patients eligible for screening of pathogenic CDH1 germline variants." (PMID 33322525, 2020). "It is important to supplement the management protocol based on more data on CDH1 mutation penetrance in sporadic gastric cancer cases among different geographic regions." (PMID 31892987, 2020). "CDH1 truncating variants are associated with risk to gastric diffuse cancer and in fact, one patient presented familial history of gastric cancer, however, all three cases presented BC or fulfilled NCCN criteria for HBOC risk." (PMID 32039725, 2020). "Later on, the association of gastric cancer and lobular breast carcinoma in families with mutations in the CDH1 gene was reported." (PMID 32886433, 2020). "For instance, interleukin (IL)-1β directly induced promoter methylation of CDH1 encoding the tumor suppressor E-cadherin in a mouse model of gastric cancer." (PMID 32678024, 2020). "One to three percent of gastric cancer patients have HDGC whose main cause is a germline mutation in the CDH1 gene in 30%–50% of cases." (PMID 32886433, 2020). "Our results highlight the clinical impact of the reported CDH1 variant running in gastric cancer families." (PMID 32664545, 2020). "The objective of this study was to assess the frequency of CDH1 V832M mutation carriers in unselected Korean gastric cancer patients with a high incidence of sporadic gastric cancer." (PMID 31892987, 2020).